ERICH4 (glutamate rich 4)
Synonyms: C19orf69; LOC100170765
Tractability: No criterion of Open Targets' tractability assessment is met for any kind of drug.
Gene: Protein-coding gene on chromosome 19 (41,443,156 to 41,444,765, forward strand). Ensembl gene ENSG00000204978.
Subcellular location (Human Protein Atlas): Nucleoplasm; Cytosol
Gene Ontology:
Molecular function: protein binding
Genetic constraint (gnomAD): Loss-of-function variants: 4 observed, 3.38 expected, observed/expected ratio (o/e) 1.18, 90% interval 0.55 to 1.89. That is too few expected variants to judge how well the gene tolerates losing a copy. Missense variants: 164 observed, 130.91 expected, observed/expected ratio (o/e) 1.25, 90% interval 1.1 to 1.43. Synonymous variants: 75 observed, 54.22 expected, observed/expected ratio (o/e) 1.38, 90% interval 1.15 to 1.68.
Homologues: Orthologues: chimpanzee ERICH4 (99% identical), dog ERICH4 (74% identical), guinea pig ERICH4 (72% identical), rabbit ERICH4 (67% identical), rat Erich4 (67% identical), mouse Erich4 (65% identical), pig ERICH4 (63% identical).
Diseases named in the same sentence as ERICH4 in open-access papers:
ERICH4 is named in the same sentence as 4 diseases in open-access papers, as found by Europe PMC text mining. Sharing a sentence is not in itself a finding about the gene and the disease. The quoted sentences say what the papers report.
basal cell carcinoma (1 paper, 2023). A carcinoma involving the basal cells. "Additionally, known as glutamate rich 4, Erich4 is relatively poorly understood, but its low expression has been associated with renal cell carcinoma and its mutational loss has been recorded in basal cell carcinoma." (PMID 36765634, 2023).
cancer (1 paper, 2023). A tumor composed of atypical neoplastic, often pleomorphic cells that invade other tissues. "Additionally, our transcriptomic analyses identified expressional changes in many cancer-associated genes, and bisulfite sequencing revealed that the antiproliferation-associated gene Erich4 was both hypomethylated and overexpressed in our experimental group." (PMID 36765634, 2023). "If this interaction is important in stemming cancer cell proliferation, it is possible that the hypomethylation and overexpression of Erich4 with BSp treatment contributed to the anticancer effects that we found in vivo." (PMID 36765634, 2023).
ERICH4 also shares sentences with these, for which no sentence is quoted: renal cell carcinoma (1 paper); tumor (1).